USP7 (ubiquitin specific peptidase 7)
Diseases named in the same sentence as USP7 in open-access papers (continued):
Sharing a sentence is not in itself a finding about the gene and the disease.
lung carcinoma (46 papers, 2015 to 2025). "USP7 reprogrammed tumor-associated macrophages and modulates anti-tumor immune response in lung cancer." (PMID 38638430, 2024). "In lung cancer, tumor-associated M2 macrophages interact with USP7 to regulate the antitumor immune response." (PMID 38034950, 2023). "USP7 could modulate the anti-tumor immune response by reprogramming tumor-associated macrophages in lung cancer." (PMID 41145464, 2025). "Collectively, the findings from this study suggest that mTOR and USP7 may serve as additional novel targets for developing strategies to prevent and treat arsenic and BaP co-exposure-caused lung cancer." (PMID 32802178, 2020). "Importantly, high level of USP7 expression was found to be associated with the poor outcome of lung cancer patients (excluding the adenocarcinoma patients)." (PMID 25519684, 2015). "In lung cancer, one study indicated that USP7 was overexpressed in lung cancer, and this overexpression was directly related to the initiation of tumors and strongly correlated with a poor outcome in cancer patients." (PMID 40006058, 2025). "PROTAC 17, the potent inhibitor of USP7, can selectively inhibit USP7 to affect tumor progression in lung cancer and prostate cancer." (PMID 38531846, 2024). "P5091 is a USP7 inhibitor that inhibits Treg activity and preserves key T effector cell function in a mouse lung cancer model." (PMID 39253578, 2024). "To further validate the specificity of the upregulation, we made siRNA-mediated USP7-knockdown (USP7-Kd) in A549 and H1299 lung cancer cells and found that USP7-Kd also markedly upregulates USP22 in both cancer cell lines." (PMID 37946202, 2023). "Studies have found that FTO can promote the expression of USP7 through demethylation and can increase the stability of USP7, which is expected to become a potential target for the treatment of human lung cancer." (PMID 34149432, 2021). "NSCLC studies have shown that high expression levels of USP5 and USP7 in lung cancer tissue promote lung cancer cell proliferation by stabilizing beta‐catenin." (PMID 33619866, 2021). "The multifaceted role of USP7 in various cancers is established, including lung cancer, colon cancer, breast cancer and leukaemia." (PMID 34469054, 2021).
lung carcinoma (continued). "Current studies have also shown that USP7 suppressed proliferation and the colony formation capacity of lung cancer cells." (PMID 34469054, 2021). "Here, we investigated the role of USP7 in TAMs and how targeting USP7 can affect immune checkpoint blockade strategy for lung cancer." (PMID 32802195, 2020). "On the other hand, high expression of FTO in lung cancer was found to decrease the m6A levels of ubiquitin-specific peptidase 7 (USP7), improve the mRNA stability of USP7, and promote the occurrence of NSCLC." (PMID 32398132, 2020). "Additional further investigation targeting PLK1 and USP7 would be interested in platinum-resistant lung cancer for clinical usage since platinum-based agents are also first in line for the treatment of NSCLC." (PMID 33207738, 2020). "When USP7 was blocked in the paclitaxel-resistant lung cancer NCI-H460TXR cells, which has resistance to mitotic catastrophe, NCI-H460TXR cells underwent apoptosis effectively." (PMID 33207738, 2020). "Second, due to its high expression in mitosis, depletion of USP7 induces apoptosis through mitotic catastrophe in prostate and lung cancer." (PMID 33207738, 2020). "The human lung carcinoma cell line H1299 was transfected with an expression cassette that drives expression of an inducible USP7 shRNA and a stable cell line was derived." (PMID 29482658, 2018). "On the contrary, another study found that USP7 inhibition elevated the PD-L1 expression in lung cancer cells, suggesting that the regulation of PD-L1 expression by USP7 is multifaceted and may be context-dependent." (PMID 40247205, 2025). "However, a related study showed that inhibiting USP7 increased the expression of PD-L1 in lung cancer cells, and higher levels of USP7 promoted tumor growth by altering the immunosuppressive characteristics of Forkhead box protein P3 (Foxp3)+ Treg." (PMID 39748950, 2024). "Moreover, combining USP7 inhibitors with anti-PD-1 monoclonal antibody therapy has shown promising therapeutic effects in lung cancer models." (PMID 39315102, 2024). "USP7 reprogrammed macrophages and modulates antitumor immune response in lung cancer." (PMID 38638430, 2024). "To test this hypothesis, we first examined if knockdown of USP7 will further suppress USP22-Ko lung cancer cell in vitro proliferation." (PMID 37946202, 2023). "The USP7 overexpression often represents weaker prognosis in neuroblastoma, lung cancer, and CRC." (PMID 37658402, 2023). "However, previous Dai’s study found that USP7 inhibition actually elevated the PD-L1 expression in lung cancer cells." (PMID 37658402, 2023). "Recent experiments in mouse models of lung cancer have shown that targeting USP7 with USP7 inhibitor P5091 upregulates the expression of PD-L1 protein in Lewis tumor cells and blocks PD-1, leading to an effective anti-tumor response in lung cancer." (PMID 37554324, 2023). "Furthermore, altered macrophage reprogramming by USP7 inhibition promotes M1 polarization of tumor-related macrophages and inhibits lung cancer cell proliferation." (PMID 35948545, 2022). "Deubiquitination plays a decisive role in lung cancer, such as USP7." (PMID 34533198, 2021). "As a typical representative of the USPs family, USP7 is also known as herpes virus-associated ubiquitin-specific protease (HAUSP) and is closely related to various diseases such as prostate cancer, colon cancer, lung cancer, and multiple myeloma." (PMID 33925279, 2021).
lung carcinoma (continued). "In general, targeting USP7, combined with the PD-1 monoclonal antibody, may provide a new avenue for clinical treatments of lung cancer." (PMID 32802195, 2020). "Furthermore, combination treatment with the mitotic kinase PLK1 inhibitor volasertib and the USP7 inhibitor P22077 showed a strong synergism through down-regulation of MDR1/ABCB1 in paclitaxel-resistant lung cancer." (PMID 33207738, 2020). "However, the cellular functions of USP7 in lung cancer remain controversial." (PMID 35948545, 2022). "In addition, USP7 gene knockout or drug suppression (P5091 or P22027) reduced the proliferation rate and colony-forming ability of lung cancer cells, while the inhibitory effect of FTO gene knockout on the growth of lung cancer cells was restored by excessive USP7 expression." (PMID 33952279, 2021). "We further tested another two USP7 inhibitors, HBX41108 and P5091, in the lung cancer cell H1299 and colon cancer cell HCT116, and found that both inhibitors dramatically upregulate USP22 in H1299 and HCT116." (PMID 37946202, 2023). "Specifically, FTO can erase the m6A in ubiquitin specific peptidase 7 (USP7) and myeloid zinc finger 1 (MZF1) mRNAs, resulting in USP7 and MZF1 overexpression, which function as oncogenes in lung cancer." (PMID 34895230, 2021). "In brief, we found that the USP7 was highly expressed concomitantly with the mitotic factors such as PLK1, CCNB1, CDC25A, and AURKB in prostate and lung cancer." (PMID 33207738, 2020). "The results of this study show that targeting USP7 can reverse the immunosuppressive effects of TME and improve the efficiency of lung cancer immunotherapy." (PMID 32802195, 2020). "Fourth, we found that combination treatment with inhibitors of USP7 and the mitotic kinase PLK1 shows a strong synergism in taxane-resistant lung cancer through down-regulation of MDR1/ABCB1." (PMID 33207738, 2020). "However, combination treatment with a USP7 inhibitor and PLK1 inhibitor exerts a strong synergistic effect in lung cancer cells resistant to paclitaxel, suggesting that co-targeting USP7 and PLK1 may be a valuable strategy for future clinical translation research." (PMID 33207738, 2020). "Inhibitors of the DUB proteins USP1, USP4, USP7, USP14, and USP33 have shown therapeutic effects in prostate cancer, lung cancer, breast cancer, and blood malignancies 24-28." (PMID 32802195, 2020). "In lung cancer, FTO downregulation increases m6A levels which then mediates downregulation of MZF1, a myeloid zinc finger protein 1 and USP7, ubiquitin-specific protease 7 due to decreased stability of their mRNA transcripts, causing an increase in lung cancer tumorigenicity." (PMID 40722726, 2025). "We found that the USP7-specific inhibitor FT671 dramatically upregulates USP22 protein in a dose-dependent manner, even at a very low concentration that barely affects cellular proliferation in lung cancer cell line A549." (PMID 37946202, 2023).
lung carcinoma (continued). "Thus, we reasoned that P5091, an Usp7 inhibitor, lowering CCDC6 levels, should sensitize even lung cancer cells that express normal level of the protein to olaparib." (PMID 28653990, 2017).
multiple myeloma (46 papers, 2015 to 2025). "More specifically, the dysregulation of USP7 expression has been linked to the onset of many malignancies, such as multiple myeloma, prostate cancer, ovarian cancer, cervical cancer, glioma, colorectal cancer (CRC), liver and brain cancer, gastric cancer, and head and neck cancer." (PMID 41157055, 2025). "For example, USP7 overexpression has been linked to bortezomib resistance, and a small molecule inhibitor (P5091) of USP7 has been shown to overcome this resistance and produce apoptosis in myeloma cells." (PMID 36768967, 2023). "Studies showed that the combination of USP7 inhibitors with bortezomib exhibited a synergistic activity against multiple myeloma, suggesting a promising therapeutic strategy for overcoming resistance to current treatments." (PMID 41157055, 2025). "More recently, it was shown that USP7 is involved in regulating plasmacytoid DCs (pDCs) phenotype and function in multiple myeloma (MM)." (PMID 40247205, 2025). "Based on experimental and molecular docking methods, USP7 inhibitors of the natural primary crystal triterpene skeleton were reported in 2018 and demonstrated inhibitory effects on myeloma cell proliferation." (PMID 38276639, 2023). "Accumulated studies have revealed that USP7 is highly upregulated in various tumors, including prostate, breast, ovarian, and colorectal cancers, as well as multiple myeloma and gliomas." (PMID 34580281, 2021). "P5091 can induce the apoptosis of multiple myeloma (MM) cells resistant to traditional therapy or bortezomib by inhibiting the activity of USP7, and can also play a synergistic role when used in combination with dexamethasone or lenalidomide." (PMID 33925279, 2021). "The increased expression of USP7/HAUSP was also reported to participate in the development of multiple cancers, such as multiple myeloma, oesophageal cancer, gliomas 16 and ovarian cancer." (PMID 33129231, 2021). "A large number of previous studies have found that USP7 exhibits a high expression signature in a variety of malignant tumors, including myeloma, prostate, hepatocellular, ovarian cancer and glioma." (PMID 33967786, 2021). "Intriguingly, the USP7 inhibitor (P5091) significantly inhibited myeloma cells’ cell growth and overcame NEK2-induced and -acquired BTZ resistance." (PMID 33967786, 2021). "USP7 is involved in hematological malignancies and the USP7 small-molecule inhibitor P5091 impaired tumor growth in multiple myeloma xenograft models." (PMID 34359655, 2021). "USP7 plays a multifaceted role and is involved in the development of a variety of tumors, including esophagus cancer, myeloma and ovarian cancer." (PMID 32002017, 2020). "USP7 nitrothiophene-based inhibitor 5091 proved to be a promising therapeutic for treatment of multiple myeloma, and its second generation inhibitor, 217564, was determined to covalently modify C223 to inhibit USP7 activity." (PMID 32850836, 2020). "Datas indicated that the USP7 inhibitor P5091 was overcoming bortezomib resistance in multiple myelomas by destabilizing NEK2." (PMID 32002017, 2020). "All these evidence strongly support the clinical investigation of USP7 inhibitors, alone or in combination, as a valid therapeutic strategy for the treatment of multiple myeloma." (PMID 32531973, 2020). "The USP7 inhibitor P5091 has been reported to induce apoptosis of multiple myeloma (MM) cells, and synergistic anti-MM effects can be exerted by multiple drugs." (PMID 32002017, 2020). "It has been reported that both the protein and mRNA levels of USP7 are highly elevated in multiple myeloma (MM), and the MM patients with higher USP7 levels have significantly poorer survival." (PMID 32300595, 2020).